GRHL2 (grainyhead like transcription factor 2)
Diseases named in the same sentence as GRHL2 in open-access papers (continued):
Sharing a sentence is not in itself a finding about the gene and the disease.
breast carcinoma (continued). "Only a minor fraction of ~ 1.5% of conserved GRHL2 peaks identified in our study was flanked by established ER⍺ binding sites in luminal breast cancer cells identified in those studies." (PMID 36691073, 2023). "Our findings reveal gene sets regulated directly or indirectly by GRHL2 in luminal breast cancer that partly overlap but also appear markedly distinct from targets identified in other tissues." (PMID 36691073, 2023). "For the negatively correlated gene cluster, TGFBR2 as well as TGFB1 showed a significant correlation in the same direction in the METABRIC data set, further establishing suppression of TGFß signaling by GRHL2 in breast cancer cells." (PMID 36691073, 2023). "GRHL2 has also been reported to be lineage-specific driver of reprogrammed estrogen signaling and an enabler of endocrine resistance in ER + breast cancer." (PMID 36864480, 2023). "Using a conditional KO model, we identify genes whose transcription is regulated by GRHL2 in luminal breast cancer cells." (PMID 36691073, 2023). "Despite the induction of EMT and enhanced migratory capacity in basal A breast cancer cells, the ultimate outcome of GRHL2 depletion in the orthotopic tumor growth and metastasis experiment reported here supports an oncogenic role of GRHL2." (PMID 36768838, 2023). "This is in agreement with earlier studies and with the fact that GRHL2 is located on chromosome 8q22 which is amplified or overexpressed in several cancer types, including breast cancer." (PMID 36768838, 2023). "The dominant response to GRHL2 depletion in luminal breast cancer cells is suppression of proliferation and we identify clusters of genes reflecting this response including direct regulation of ETS and E2F transcription factors by GRHL2." (PMID 36691073, 2023). "GRHL2 is located on chromosome 8q22 that is frequently amplified in many cancers, including breast cancer, colorectal cancer and oral squamous cell carcinoma." (PMID 36691073, 2023). "We report genome-wide binding sites of the transcription factor GRHL2 that are conserved across 3 human luminal breast cancer cell lines." (PMID 36691073, 2023). "In breast cancer patients, GRHL2 expression was increased in all subtypes and inversely correlated with overall survival in basal-like breast cancer patients." (PMID 36768838, 2023). "In this study, we identify genomic binding sites of GRHL2 shared among 3 luminal breast cancer cell lines and find that only a small subset of these GRHL2 peaks is associated with ER binding sites." (PMID 36691073, 2023). "Further, the Cistrome DB analysis showed that the GRHL2 protein had regulatory potential for SCIN in breast cancer cells." (PMID 38201443, 2023). "In order to evaluate the clinical relevance of GRHL2 in breast cancer, GRHL2 alterations were examined in a series of published cohorts." (PMID 36768838, 2023). "GRHL2 is located on chromosome 8q22 and amplified or overexpressed in several cancer types, including breast cancer." (PMID 36768838, 2023). "Among EMT-related genes, direct regulation of CLDN4 is corroborated but several targets identified in other cells (including CDH1 and ZEB1) are ruled out by both ChIP- and Bru-seq as being directly controlled by GRHL2 in luminal breast cancer cells." (PMID 36691073, 2023). "Our previous study demonstrated that GRHL2 was more highly expressed in breast cancer tissues than in normal tissues, and the high expression of GRHL2 was associated with a worse prognosis for breast cancer patients." (PMID 38201443, 2023). "We made use of a cohort of 867 untreated breast cancer patients (MA-867 dataset) and ranked patients in 4 quartiles according to the level of GRHL2 expression." (PMID 36691073, 2023). "The association with GRHL2 of gene clusters in the KO model predicts the correlation with GRHL2 expression in breast cancer patients." (PMID 36691073, 2023).
breast carcinoma (continued). "The expression of GRHL2 mRNA and protein was significantly higher in tumor versus normal tissue for all breast cancer subtypes analyzed." (PMID 36768838, 2023). "Our data do confirm CLDN4 as a direct target gene with GRHL2-binding in the promoter region and transcriptional suppression in response to GRHL2 depletion in luminal breast cancer cells." (PMID 36691073, 2023). "Altogether, this study uncovers gene sets regulated directly or indirectly by GRHL2 in luminal breast cancer, identifies novel GRHL2-regulated genes, and points to distinct GRHL2 regulation of EMT in luminal breast cancer cells." (PMID 36691073, 2023). "For genes showing sustained up- or downregulation in response to GRHL2 deletion, we explore correlations with GRHL2 expression in breast cancer patients." (PMID 36691073, 2023). "Further, it is expressed in basal A where its depletion triggers a slow growth/high motility phenotype and in vivo, growth arrest is the dominant response to GRHL2 depletion, in line with its overexpression in breast cancer patients." (PMID 36768838, 2023). "Our study using a panel of >50 human breast cancer cell lines confirms and extends an earlier report showing that GRHL2 is downregulated in basal B breast cancer." (PMID 36768838, 2023). "As expected, based on earlier reports in other cell types, E-cadherin is downregulated in response to GRHL2 knockout in luminal as well as basal A breast cancer cells." (PMID 36768838, 2023). "GRHL2 regulates the estrogen receptor signalling in breast cancer by directly regulating the expression of ER target genes." (PMID 35269877, 2022). "In carcinoma or breast cancer, GRHL2 can suppress ZEB1 to block TGF-β-mediated EMT and resistance ability." (PMID 34572451, 2021). "In this regard, Cocce and colleagues identified the GPI-anchored membrane protein, LYPD3, as a “druggable” downstream target of FOXA1 and the transcription factor, GRHL2 (Grainyhead Like Transcription Factor 2) in endocrine-resistant breast cancer." (PMID 34680352, 2021). "In breast cancer, GRHL2 down-regulated Smad and ZEB1 expression thus inhibited TGF-β-induced tumor metastasis and ultimately limited the cancer progression." (PMID 33931584, 2021). "Fourthly, GRHL2 expression suppresses stemness properties in CD44high/CD24low mesenchymal subpopulation cells of breast cancer cells and restores the anoikis sensitivity by altering intracellular H2O2 ROS levels." (PMID 32974388, 2020). "GRHL2 has been identified as an MET inducer in breast cancer, where it forms a mutually inhibitory feedback loop with ZEB1, an EMT-TF." (PMID 32676163, 2020). "Gene correlation analysis of a breast cancer cohort showed that higher expression of GRHL2 is correlated with worse relapse-free survival in Luminal A, Luminal B, HER2+, and Basal-like subtypes." (PMID 32974388, 2020). "GRHL2 expression is enriched in human breast cancer stem cell-like subpopulation and is included in a 31-gene signature predictive of distant metastasis in estrogen receptor–negative breast cancer cohorts." (PMID 32974388, 2020). "In general, the GRHL2/ZEB1 feedback loop was identified as a key regulator of EMP and associated traits in breast cancer, lung cancer, colorectal cancer and ovarian cancer." (PMID 32676163, 2020). "GRHL2 suppresses EMT in a breast cancer cell line by directly repressing the ZEB1 promoter, while key EMT suppressors are directly transactivated by GRHL2, including MIR200B, MIR200A, MIR429 and Ovol2." (PMID 32005677, 2020). "Through the application of VULCAN to the activation of the ER in breast cancer, we were able to identify multiple previously characterized cofactors of the ER along with GRHL2 as a potential co-repressor of the ER." (PMID 31084623, 2019).
breast carcinoma (continued). "In breast cancer samples B7 and B13, we detected in concordance with the ATAC-seq data increased accessibility for GRHL2, FOXA1, and ZNF121, a zinc finger protein, which was recently implicated in regulation of cell proliferation and breast cancer development." (PMID 31604930, 2019). "These earlier data combined with the link between GRHL2 expression and patient survival indicate a significant role for GRHL2 in the progression of breast cancer." (PMID 31084623, 2019). "VULCAN analysis of estrogen receptor activation in breast cancer highlights the key components of the estrogen receptor complex alongside a novel interaction with GRHL2." (PMID 31084623, 2019). "GRHL2 expression has been shown to be elevated in epithelial luminal cells and downregulated in mesenchymal breast cancer cell lines." (PMID 30154364, 2018). "GRHL2 expression is usually low in breast cancers that exhibit features of EMT, such as the claudin-low subclass, but when it is overexpressed it can suppress TGFβ-induced EMT." (PMID 27367735, 2016). "All these data indicate a physiological role of Grhl2 in regulating epithelial gene expression and epithelial phenotype in breast cancer cells, as reported in our article." (PMID 23610592, 2013). "Our results have shown the expressional association and clinical relevance of six genes (CDH2, FN1, CITED2, CTNNB1, and CTNNA3) together with GRHL2 for breast cancer metastases." (PMID 23441166, 2013). "In our article we report that Grhl2 plays an essential role in the determination of epithelial phenotype of breast cancers, epithelial-to-mesenchymal transition (EMT) and tumor progression." (PMID 23610592, 2013). "This study demonstrates a novel strategy to use transcriptomic data for elucidating the genomic impact of a new prognostic transcription factor, GRHL2, on breast cancer metastasis-free survival." (PMID 23441166, 2013). "They concluded that their findings defined a major role of Grhl2 in the suppression of oncogenic EMT in breast cancer cells." (PMID 23610592, 2013). "We have become interested in exploring the role of the Grainy head-like 2 (GRHL2) transcription factor in mediating the poor outcomes observed in individuals with breast cancer who have amplification of the 8q22.3 locus." (PMID 23441166, 2013). "Training on public gene expression profiles of 995 breast cancer patients, this method prioritized one gene-set pair (GRHL2, CDH2, FN1, CITED2, MKI67 versus CTNNB1 and CTNNA3) from all 2717 possible gene-set pairs (GSPs)." (PMID 23441166, 2013). "In this manuscript, we demonstrate the identification of a new biomarker, GRHL2, together with other six genes to play a breast cancer prognostic role, using RXA-GSP." (PMID 23441166, 2013). "Grhl2 is expressed in breast cancer cells in epithelial status and is down-regulated when tumor cells are induced to undergo EMT by signaling pathways such as TGFβ." (PMID 23610592, 2013). "Extensive bioinformatics analyses of large breast cancer microarray datasets revealed a remarkable level of correlation between the expression of Grhl2 and E-cadherin." (PMID 23284647, 2012). "Collectively, these data indicate that Grhl2 is the essential transcription factor that determines the epithelial phenotype of breast cancers." (PMID 23284647, 2012). "GRHL2 is lost in more mesenchymal-like breast cancers, such as TNBC and claudin-low, suggesting that signaling converging on ZEB1 and miR-200c are important not just for EMT, but also for anoikis." (PMID 23185507, 2012). "Our study indicates that Grhl2 is the essential transcription factor that determines the epithelial phenotypes of breast cancers." (PMID 23284647, 2012). "In this study, we demonstrate that Grhl2 is the epithelial specific transcription factor that determines the epithelial phenotype of breast cancers, and plays a critical role in tumor progression." (PMID 23284647, 2012).
breast carcinoma (continued). "Here, by analyzing large expression profiles of human breast cancer cells, we found an extraordinary correlation between the expression of Grainyhead transcription factor Grhl2 and epithelial marker E-cadherin." (PMID 23284647, 2012). "Examination of expressions of Grhl2 and E-cadherin in human breast cancers reveals that these epithelial genes are not only expressed in primary tumors but also a majority of metastatic tumors." (PMID 23284647, 2012). "To evaluate the clinical relevance of Grhl2 in breast cancer patients, we used a large public microarray database." (PMID 23284647, 2012). "In conclusion, our findings indicate that Grhl2 plays an essential role in the determination of epithelial phenotype of breast cancers, EMT and tumor progression." (PMID 23284647, 2012). "Using this approach, we readily could detect GRHL2 granular structures in the nucleus of breast cancer cells." (PMID 40889682, 2025). "Finally, mechanisms that drive the evolution of KDM4C-amplified basal breast cancer to prevent GRHL2 methylation and histone H3 clipping by CTSL would need to be delineated in future studies." (PMID 40457074, 2025). "In luminal breast cancer, GRHL2 has been demonstrated to directly or indirectly regulate sets of genes involved in regulation of cell proliferation, thus substantiating a fundamental role of GRHL2 in regulation of tumor growth." (PMID 40889682, 2025). "Consequently, we not only elucidated the epigenetic differences among breast cancer cell lines but also revealed a novel function of GRHL2 in distinguishing basal-like and mesenchymal characteristics in these cells." (PMID 38429368, 2024). "Integrating GRHL2 status into pathologic evaluation and clinical decision making may help individualize breast cancer treatment based on the potential to activate dissemination programs through this plasticity factor." (PMID 39199676, 2024). "GRHL2 is described in several breast cancer-related articles, mainly in luminal BC." (PMID 39208653, 2024). "We further investigated the relation between GRHL2 and CD73 protein expression levels by IHC on samples of human breast cancer tissue, choosing a set of 10 GRHL2-high, 10 GRHL2-low (based on RNA-seq), and 10 metaplastic breast adenocarcinoma patient tumors as these were expected to be heterogeneous." (PMID 38706844, 2024). "Interestingly, high GRHL2 expression increases stem cell markers and self-renewal characteristics in a luminal breast cancer cell, as well as markers of dormancy." (PMID 39199676, 2024). "GRHL2 is located on chromosome 8q22.3, a region frequently amplified in breast cancer." (PMID 39199676, 2024). "Here, we showed that ER-positive breast cancer cells overexpressing GRHL2 significantly increased epithelial markers and behavior as compared to those with only endogenous levels of GRHL2, indicating that GRHL2 retains its potent role in epithelial identity when expressed at high levels." (PMID 39199676, 2024). "Examination of primary breast cancers showed an association of GRHL2 protein expression with ER-positive but not ER-negative breast cancers." (PMID 39199676, 2024). "Our findings show that GRHL2 represents a candidate therapeutic target for luminal breast cancer." (PMID 36768838, 2023). "Our findings show that GRHL2 is absent in basal B breast cancer cells, and it is expressed in luminal breast cancer cells where its depletion causes an arrested proliferation." (PMID 36768838, 2023). "GRHL2 may play a dual role in breast cancer and a tumor- or metastasis-suppressive function has been related to its ability to suppress EMT, stemness, and invasion in cell line models and clinical samples." (PMID 36768838, 2023). "Indeed, among the shared GRHL2 peaks in luminal breast cancer cells ~ 5% was flanked by an ER⍺ binding motif within ± 1000 bp." (PMID 36691073, 2023). "Indeed, GRHL2 expression was negatively correlated with metastasis-free survival in breast cancer patients." (PMID 36691073, 2023).
breast carcinoma (continued). "In addition to a role in craniofacial, neurulation and ectodermal defects, GRHL2 is thought to play a role in multiple types of cancer as a tumour suppressor or promoter and has predictive prognostic value in breast cancer and colorectal cancers." (PMID 37364051, 2023). "Our exclusive focus on GRHL2 binding sites that are conserved across three luminal breast cancer cell lines may have selected for those sites binding only GRHL2." (PMID 36691073, 2023). "Notably, GRHL2 can regulate ER⍺ signaling output in hormone receptor positive breast cancer by co-occupying enhancer elements with FOXA1, GATA3, and ER⍺." (PMID 36691073, 2023). "In this study, we investigated the role of GRHL2 in different breast cancer subtypes." (PMID 36768838, 2023). "Likewise, the findings reported in our study represent candidate GRHL2-regulated genes and pathways in luminal breast cancer that partly overlap but are also distinct from GRHL2 regulation in normal epithelia and other cancer types." (PMID 36691073, 2023). "Furthermore, the knockdown of GRHL2 in breast cancer cells led to the induction of the TGF-β/Smad target gene, CTGF." (PMID 35269877, 2022). "In the context of breast cancer, GRHL2 induces an epithelial phenotype in mammary cells and its expression prevents tumour initiation in breast cancer xenografts, sensitises breast cancer cells to chemotherapy, and suppresses the emergence of treatment-resistant cancer stem cells." (PMID 35269877, 2022). "Erbb3 shares a similar expression pattern to Grhl2 during breast cancer in the luminal epithelium." (PMID 35269877, 2022). "Additionally, the overexpression of GRHL2 can effectively inhibit tumour invasion and migration in gastric and breast cancer." (PMID 35090432, 2022). "It has been recently reported that FOXA1/GRHL2 collaboration could establish a targetable pathway in endocrine therapy-resistant breast cancer, and facilitate depositing H3K4me1 at potential enhancer elements by recruiting the chromatin modifier MLL3." (PMID 34395436, 2021). "However, the controversial roles of GRHL2 have been described in breast cancer, in which overexpression of GRHL2 drives EMT phenotype via binding to ERBB3 promoter." (PMID 34572451, 2021). "At the molecular level, GRHL2 directly regulates the expression of the EGFR family member ERBB3 and the Wnt ligand Wnt7A, and overexpression of GRHL2 in metastatic breast cancer cells exhibit increased anchorage-independent growth, migratory and invasive potential." (PMID 32974388, 2020). "Given the central role of the ER in breast cancer development and GRHL2’s own ability to regulate EMT, the discovery that ER recruits GRHL2 leading to the altered eRNA production is an important step in enhancing our understanding of breast cancer and tumorigenesis." (PMID 31084623, 2019). "In addition, ZEB1 transcriptionally represses genes of the miR-200 family, and that GRHL2 up-regulates the expression of miR-200b/c family members in breast cancer cells." (PMID 29110737, 2017). "In breast cancer, GRHL2 has been reported to suppress anoikis resistance and mammosphere formation." (PMID 26887977, 2016). "Using a collection of 1678 independent human breast cancer samples, we identified and validated a new GRHL2-mediated gene-set pair that could effectively stratify patients showing significant differences in metastasis free survival." (PMID 23441166, 2013). "Our data suggest that Grhl2 could be the transcription factor that drives the expression of miR-200 in breast cancer cells." (PMID 23284647, 2012). "Our data showed that Grhl2 determines the epithelial phenotypes of breast cancers." (PMID 23284647, 2012). "Moreover, this study shows that adenosine produced by GRHL2-depleted breast cancer cells (or provided as a stable analog) can augment the recruitment of CD8 T cells, in addition to its previously established role as a suppressor of T cell-mediated cytotoxicity." (PMID 38706844, 2024).